SFN (stratifin)
Diseases named in the same sentence as SFN in open-access papers (continued):
Sharing a sentence is not in itself a finding about the gene and the disease.
periodontal disease (1 paper, 2022). "Epigenetic inactivation (hyper-methylation) of SFN has been associated with cancer and periodontal disease." (PMID 36438010, 2022).
pneumocystis pneumonia (1 paper, 2022). "Finally, in patients with infectious pneumonia (n = 19), while four and six patients were positive for KL-6 and SP-D, respectively, only one patient (pneumocystis pneumonia) was positive for SFN." (PMID 36195613, 2022).
rectal cancer (1 paper, 2022). A primary or metastatic malignant neoplasm that affects the rectum. "Interestingly, SFN and IGF2BP2, which were more highly expressed in the metastases of poor-outcome patient I, were also associated with shorter overall survival in a large cohort (n = 165) of rectal cancer patients based on data from the Kaplan–Meier plotter database." (PMID 35565214, 2022).
renal fibrosis (1 paper, 2025). A final common manifestation of a wide variety of chronic kidney diseases characterized by glomerulosclerosis and tubulointerstitial fibrosis. "In summary, we identified five key genes (SFN, ARHGAP9, VSIG4, ISG20, CD3G) that can distinguish patients with renal fibrosis from controls, making them potential biomarkers for disease diagnosis and treatment monitoring." (PMID 41218386, 2025).
Sotos syndrome (1 paper, 2022). Sotos syndrome is a rare multisystemic genetic disorder characterized by a typical facial appearance, overgrowth of the body in early life with macrocephaly, and mild to severe intellectual disability. "In conclusion, we propose that NSD1 may participate in Sotos syndrome’s mechanism of action by regulating the function of lncRNA, inducing the down-expression of GSC, NDRG2 and SORBS1 and the up-expression of SFN and ZNF883." (PMID 35888078, 2022).
thyroid (1 paper, 2025). "In the comparison between PTC and benign thyroid samples, SFN and CCNA1 were significantly upregulated, whereas FOS, HSPA5, JUN, CREB1, and MAP2K6 exhibited significant downregulation, supporting the findings obtained from the RT-qPCR analysis." (PMID 40722651, 2025).
tongue squamous cell carcinoma (1 paper, 2015). A squamous cell carcinoma that arises from the tongue.
urinary bladder tumor (1 paper, 2008). "We observed hypermethylated CDH1, SFN, and RARB genes in the normal-adjacent tissue of urinary bladder tumor." (PMID 18702824, 2008).
tumor (87 papers, 2005 to 2026). "SFN expression was associated with tumor size, degree of differentiation, TNM stage, and vascular invasion (P < 0.05)." (PMID 37587914, 2023). "The expression of SFN was positively associated with large tumor size, poor differentiation, advanced Tumor Node Metastasis (TNM) stage, vascular invasion, and poor prognosis in HCC." (PMID 37587914, 2023). "In contrast, in late tumor stages, high SFN expression led to significantly reduced survival (p = 0.0039), indicating the association of SFN with tumor progression." (PMID 37128318, 2023). "Among histopathologically normal tumor-adjacent urinary bladder tissues, the same methylation pattern was found, except in one sample which showed only the unmethylated alleles for SFN gene." (PMID 18702824, 2008). "SFN has a tumor suppressor role, so the loss of SFN is required to initiate metastasis, and at a progressive stage, mutated SFN overexpression might behave more like an oncogene; hence higher expression of SFN promotes metastasis." (PMID 37128318, 2023). "For example, our computational analysis showed that the increased expression of SFN and SPP1 were associated with higher tumor grades and worse survival outcomes, indicating that SFN and SPP1 might act as oncogenes in HCC." (PMID 33221766, 2020). "We observed the upregulation of genes associated with positive anti-tumor activity, including NR3C1, BRCA1, BRCA2 and SFN." (PMID 40043049, 2025). "Single-cell localization analysis of the risk genes demonstrated that only ADH7, SFN, WWC1, PAK6, and TEAD3 were detectable in the single-cell data, with TEAD3 being predominantly expressed in tumor cells." (PMID 41034991, 2025). "Abundant experimental evidence suggests a correlation between aberrant SFN expression and tumor metastasis and invasion." (PMID 37946061, 2024). "Biologically, downregulation of SFN suppressed tumor cell proliferation, epithelial–mesenchymal transition (EMT), invasion, and migration in vitro and tumor growth in vivo." (PMID 37587914, 2023). "SFN has been reported to induce apoptotic cell death and cell cycle arrest in several tumor cell lines and to impede tumor growth, metastasis, and angiogenesis in animal models." (PMID 37107528, 2023). "In tumor tissue, SFN expression is measured at 5.47 log2 (TPM+1) compared to 4.21 log2 (TPM+1) in normal tissue." (PMID 37128318, 2023). "In this study, we found that SFN was upregulated in HCC cell lines and tissues and was positively associated with tumor size, poor differentiation, Tumor Node Metastasis (TNM) stage, and vascular invasion." (PMID 37587914, 2023). "SFN, also known as 14-3-3σ, has been described both as a tumor suppressor gene as well as a tumor oncogene." (PMID 36648863, 2023). "We analyzed the SFN expression based on patients' age, race, tumor grade, tumor stage, and nodal status." (PMID 35547358, 2022). "Nonetheless, SFN has been identified as well as a tumor suppressor/modulator gene in colon, ovaries, breast, bladder, and lung and its expression was downregulated in these cancers." (PMID 36160032, 2022). "In the LINC01128/miR-383-5p/SFN axis, the upregulation of LINC01128 and Stratifin (SFN) was accompanied by miR-383-5p downregulation in CC tissues and cells and was related to tumor development and poor prognosis." (PMID 36313570, 2022). "Many recent studies have shown that stratifin is a critical marker in the process of tumor progression." (PMID 35281796, 2022). "In contrast, high expression of SFN in tumors of size <5 cm can present its oncogenic effect in very early stages of BC, such as tumor initiation." (PMID 36160032, 2022).
tumor (continued). "The results showed that SFN was highly upregulated among Asians, among 41–60-year-old individuals, among those with a positive nodal status, and among grade 3 tumor patients." (PMID 35547358, 2022). "Results of immunohistochemistry (IHC) and expression analysis demonstrated that the expression of SFN in primary tumor tissue from NSCLC patients was significantly higher than that in adjacent non-tumor tissues (p < 0.01)." (PMID 34553022, 2021). "Our results showed that the expression level of SFN in NSCLC tumor samples was significantly higher than those in adjacent non-neoplastic tissues (p < 0.001)." (PMID 34553022, 2021). "The expression of SFN in recurrent NSCLC patients after ATC was significantly higher than in primary tumor tissues (p < 0.001)." (PMID 34553022, 2021). "The results of RT-PCR analysis as well as bioinformatics analysis consistently demonstrated that the expression of RWDD4, SDHC, SEPT7, and SFN was downregulated in the tumor tissues as compared with that in adjacent non-tumor tissues." (PMID 32156290, 2020). "Cytoplasmic expression of SKP1 was found to be significantly associated with stratifin (SFN) positivity, tumor malignancy, and unfavorable patient outcomes." (PMID 33329729, 2020). "One of these genes was associated with mitochondrial fission (fission 1, or FIS1), one with apoptosis (bcl-2 homologous antagonist killer, or BAK1) and one with tumor suppression (stratifin, or SFN)." (PMID 30404157, 2018). "We found SFN to be expressed −10.49× less in EAC tumor tissue compared to normal esophagus (P < 0.0001)." (PMID 29868478, 2018). "SFN (Stratifin, also known as 14-3-3σ) has been described as a putative tumour suppressor involved in cell cycle progression and epithelial polarity." (PMID 27374210, 2016). "From the left, the first bar (+/+) shows the mean (+SD) when both monocytes and tumor cells were pre-incubated for 20 min with sFn." (PMID 16925817, 2006). "The presence of sFn on tumor cells enhances monocyte binding, probably by upregulating αMβ2 binding to sFn coated CD54 (B), which is consistent with our results and with previous reports." (PMID 16925817, 2006). "Conversely, monocyte pre-treatment with anti-αMβ2 monoclonal antibody only inhibited adherence by 22.5 ± 2.6% to untreated A375 cells, and by 80 ± 0.5% to sFn pre-treated tumor cells (P < 0.05 compared to untreated A375 cells)." (PMID 16925817, 2006). "From the left, the first bar (+/+) shows the mean (+SD) inhibition when both monocytes and tumor cells were pre-incubated for 20 min with sFn." (PMID 16925817, 2006). "Since sFn levels are elevated in many cancer patients, peripheral blood monocytes and circulating tumor cells undergoing metastasis would likely be coated in sFn, reducing their ability to adhere to each other." (PMID 16925817, 2006). "Taken together, these results would suggest that, in vivo, elevated levels of circulating sFn would result in its binding to both tumor cells and monocytes, leading to an ongoing immunosuppression." (PMID 16925817, 2006). "sFn inhibits monocyte adherence and cytotoxicity of tumor cells by blocking αLβ2 and αMβ2 binding to tumor cell CD54." (PMID 16925817, 2006). "Blocking of the fibrin(ogen) binding sites on both monocytes (αMβ2) and tumor cells (CD54), prior to sFn treatment significantly (P < 0.05) reduced sFn mediated inhibition of monocyte/tumor cell adherence under flow conditions." (PMID 16925817, 2006). "Stratifin is expressed in epithelial keratinocytes and possesses tumor suppressing activity." (PMID 40004538, 2025). "Based on the prior literature on related tumor types, we hypothesized that two additional potential markers may be of use: stratifin (SFN) and glutathione S-transferase Pi (GSTP1)." (PMID 40004538, 2025). "Thus, the activation of SFN by our identified peptides indicates that the cells are losing their tumor characteristics." (PMID 40043049, 2025).
tumor (continued). "Tumour samples from Sudan exhibited altered expression of S100A7, S100A9, glutathione transferase, lactoglobulin, and stratifin, while normal controls compared to tumours showed changes in ferritin light subunit, fast skeletal myosin, fibrinogen, and a hypothetical protein." (PMID 39982954, 2025). "SFN promotes cell proliferation, migration, invasion, and tumor growth and may be an oncogene in HCC." (PMID 37587914, 2023). "Interestingly, one study found the expression of SFN to increase with tumor progression; however, the driving mechanism behind the increased expression has not been investigated." (PMID 37455903, 2023). "In line with this, our study also found that positive expression of SFN in Cluster_1 could indicate the potential for tumor proliferation in these patients." (PMID 37398672, 2023). "SFN negatively regulates the cell cycle and suppresses tumor." (PMID 36160032, 2022). "Analysis based on tumor grade showed increased SFN expression in grade 3 PC." (PMID 35547358, 2022). "CDK1, PITX2, PRKAA2, and SFN were all upregulated in the tumor tissue of clinical samples." (PMID 35592706, 2022). "In CC cells, overexpression of miR-383-5p showed anti-tumor effects by inhibiting SFN expression." (PMID 36313570, 2022). "Furthermore, we analyzed the expression level of SFN from The Cancer Genome Atlas (TCGA) dataset and found that the expression of SFN in NSCLC tumor samples was also significantly higher than that in normal lung tissues (p < 0.001)." (PMID 34553022, 2021). "In addition, previous study reported that SFN gets involved with multiple kinds of tumor progression including breast, liver, ovarian, and renal tumors." (PMID 33742334, 2021). "The hypermethylation of SFN is a reliable biomarker for neuroblastic tumor diagnosis." (PMID 32528944, 2020). "We predicted it may exert tumor-promoting roles by coexpressing with SFN which had been demonstrated to be oncogenic previously as follows: SFN protein was previously identified to be upregulated in HCC via proteomics analyses." (PMID 32382578, 2020). "For instance, several studies have demonstrated that 14-3-3σ (also known as stratifin or HME1) functions to suppress tumor formation in breast tissue and that its expression becomes significantly reduced by hypermethylation of its promoter region during tumorigenesis." (PMID 29321819, 2017). "The same approach that identified SFN as a tumour suppressor in HER2-induced tumorigenesis was also applied to the systematic exploration of recurrent CNAs in other models, yielding a list of candidate genes that may underlie these driver-specific events." (PMID 27374210, 2016). "In addition, this finding suggests that SFN immunoreactivity increases in the stroma with tumour development and progression." (PMID 25167778, 2014). "We hypothesized that sFn may also affect leukocyte adherence, recognition, and killing of tumor cells." (PMID 16925817, 2006). "Having demonstrated that specific sFn blocking peptides reversed sFn inhibition of monocyte/tumor cells adherence, experiments using fluorescently labeled fibrinogen to prepare sFn were performed to observe whether sFn binding to cells was also decreased." (PMID 16925817, 2006). "Extrapolation of these results to the physiological setting would suggest that, in cancer patients with elevated levels of sFn, monocytes and circulating tumor cells would bind sFn, resulting in the inability of monocytes to adhere to, and kill, tumor cells, resulting in enhanced metastasis." (PMID 16925817, 2006). "However, accumulating evidence indicates that SFN also promotes tumor progression." (PMID 35936690, 2022).
tumor (continued). "Thus, stratifin has been suggested to be a potential tumor suppressor." (PMID 34372798, 2021). "After systematic data curation, four upregulated (YWHAB, TXNDC12, MYL6B, SFN) and four downregulated (FN1, PSMB6, PRDX4, PEA15) markers in miRNA-overexpressed tumor secretomes were identified." (PMID 37128318, 2023). "Taken together, these data demonstrated that SFN promoted HCC cell proliferation, migration, and invasion in vitro and tumor growth in vivo." (PMID 37587914, 2023). "In the current study, we further showed that SFN facilitated HCC cell proliferation, migration, invasion, tumor growth, and EMT by activating Wnt/β-catenin signaling." (PMID 37587914, 2023). "For instance, the cyclin-dependent kinase inhibitors (CDKs), CDKN1A (p21Cip1), CDKN1B (p27Kip1), and CDKN2A (p16Ink4A), reprimo (RPRM), stratifin (SFN), and CDK1 are all frequently hypermethylated and play various roles in tumor radioresistance." (PMID 37455903, 2023). "In conclusion, SFN is overexpressed in HCC tissues and cell lines, and SFN expression is correlated with tumor size, differentiation, vascular invasion, and TNM stage." (PMID 37587914, 2023). "Among the upregulated proteins, we found that most were cancer-related proteins such as S100 family proteins, SFN, LDHA, and HSPB1, which all play important roles in tumor migration and invasion." (PMID 35936690, 2022). "Among the upregulated proteins, S100 family proteins, SFN, LDHA, and HSPB1 were all cancer-related proteins, which play important roles in tumor migration and invasion." (PMID 35936690, 2022). "The protein levels of PRKAA2, SFN, and CDK1 were upregulated in tumor tissue on the basis of the Human Protein Atlas (HPA) database." (PMID 35592706, 2022). "Compared with the corresponding normal tissue, the qRT-PCR ultimately confirmed the upregulation of SFN, PRKAA2, PITX2, and CDK1 in tumor tissue." (PMID 35592706, 2022). "For data validation, the expression of the SFN gene, the LINC01343, and CCDC18-AS1 lncRNAs (which were determined by bioinformatic analysis) was analyzed by qRT-PCR in tumor and paired control breast tissues." (PMID 36160032, 2022). "Of note, the roles of stratifin, p63 and IKK in tumor development have been demonstrated to be cell context-specific." (PMID 34136411, 2021). "Differential methylation of the ITGA4, SFN, ITGA2, and PIK3R1 genes allowed the discrimination between normal and tumour tissue and correlated with patient survival." (PMID 34944974, 2021). "We found that overexpression of the identified driver genes, stratifin (SFN) and SPP1, correlates with tumor grade and poor survival in HCC and promotes HCC cell proliferation." (PMID 33221766, 2020). "In our study, we also discovered abnormal expression of some tumor suppressor genes, such as IGFBP5 and SFN, which high expressed in the Mcfips, but low in Hips." (PMID 28423718, 2017). "Correlation tests showed analogous directional relationships of tumor PGR, PTEN and SFN mRNA expression across the range of observed BMI values." (PMID 28476021, 2017). "Unexpectedly, we found the core promoter regions of two tumor suppressor genes, CDH1 and SFN, were demethylated in three EAC samples." (PMID 25286960, 2014). "In our MSP analysis performed on DNA obtained from fresh tumor samples, a hypermethylated pattern predominated for CDH1 and SFN genes." (PMID 18702824, 2008). "Tumor samples consistently exhibited elevated expression levels of SFN, SPP1, and NDRG1 genes, regardless of being paired or unpaired, in comparison to non-tumor samples." (PMID 39066845, 2024). "To further delineate the crucial target gene, we initially conducted a comparative analysis of SPP1, NDRG1, SFN and LDHA mRNA expression levels in clinical samples of HCC and adjacent non-tumor tissues, as well as various HCC cell lines and normal liver cell lines." (PMID 39066845, 2024). "However, overexpression of SFN promoted cell proliferation, EMT, invasion, and migration in vitro and tumor growth in vivo." (PMID 37587914, 2023).